CCR6 (C-C motif chemokine receptor 6)
Diseases named in the same sentence as CCR6 in open-access papers (continued):
Sharing a sentence is not in itself a finding about the gene and the disease.
cystic fibrosis (1 paper, 2020). Autosomal recessive disorder caused by pathogenic variants in the CFTR gene (cystic fibrosis transmembrane conductance regulator), which encodes a chloride and bicarbonate channel expressed in epithelial cells, and follow the diagnosis criteria. "Taken together, the here acquired results suggest that pathologically increased CCL20 levels in cystic fibrosis airways induce CCR6-mediated lung homing of circulating human ILC2s." (PMID 32457736, 2020).
End Stage Liver Disease (1 paper, 2015). Final stage of a liver disease when the liver failure is irreversible and LIVER TRANSPLANTATION is needed. "Moreover, in patients with AH, CCR6 hepatic expression positively correlated with important prognostic scores such as METAVIR (p = 0.014), MELD (Model for End-stage Liver Disease) (p = 0.005), and Maddrey’s (p = 0.002) and ABIC (p = 0.043) scores." (PMID 26691857, 2015).
endotoxemia (1 paper, 2024). "In the context of the present study, we examined CCR6 and CXCR6 expression to evaluate the efficiency of post-prandial gut barrier immune function against dietary endotoxemia." (PMID 39457699, 2024).
Fabry disease (1 paper, 2024). Fabry disease (FD) is a progressive, inherited, multisystemic lysosomal storage disease characterized by specific neurological, cutaneous, renal, cardiovascular, cochleo-vestibular and cerebrovascular manifestations. "Moreover, studies observed an increase in blood lymphocyte counts, with notable elevations in specific T cytotoxic cell subsets (CCR4+CXCR3+ and CCR6+), as well as the presence of MHCII+ CD1d+ CD11b+ CD31+ monocytes in patients with Fabry disease." (PMID 39596318, 2024). "Furthermore, patients with Fabry disease exhibit elevated blood lymphocyte counts, increased levels of specific T cytotoxic cell subsets (CCR4+CXCR3+ and CCR6+), higher numbers of MHCII+ CD1d+ CD11b+ CD31+ monocytes, and notable tissue infiltration by macrophages and B cells." (PMID 39596318, 2024).
fungal infections (1 paper, 2020). "CCR6+ ILC3s also produce IL-17 and protect from fungal infections, whereas CCR6− ILC3s down-regulate RORγt and IL-22, up-regulate the TF T-bet." (PMID 32733432, 2020).
head and neck squamous cell carcinoma (1 paper, 2022). A squamous cell carcinoma that arises from any of the following anatomic sites: lip and oral cavity, nasal cavity, paranasal sinuses, pharynx, larynx, and salivary glands. "On the other hand, previous study showed a consistent pattern of CCR6 down-regulation in the cell lines and tissues of metastatic head and neck squamous cell carcinoma." (PMID 36612054, 2022).
HIVinfection (1 paper, 2020). "Thus, we furthertested the immunological/virological effects of T0070907 in flowcytometry-sorted memory CCR6+ and CCR6- T cells on HIVinfection in vitro." (PMID 33089034, 2020). "In agreement, T0070907 upregulated the expression of CH25H mRNA inTCR-activated CCR6- non-Th17 cells (data not shown), further explainingtheir relative resistance to HIV infection." (PMID 33089034, 2020).
hypertriglyceridemia (1 paper, 2025). A laboratory test result indicating elevated triglyceride concentration in the blood. "Patients with hypertriglyceridemia displayed reduced frequencies of CCR6+IL-23R+IFN-γ+ cells, whereas normal HDL levels were associated with CCR6 expression and IL-17A production." (PMID 41300932, 2025). "Patients with hypertriglyceridemia (triglycerides > 150 mg/dL) showed a lower frequency of Th17.1 cells (CCR6+IL-23R+IFN-γ+) compared with those with normal triglyceride levels." (PMID 41300932, 2025).
immune deficiency (1 paper, 2013). "In order to confirm that the phenotype observed in CCR6KO and CXCR3KO mice was specifically due to ablation of CCR6 and CXCR3 in T cells (not a general immune deficiency), CD4+ T cells from CCR6KO or CXCR3KO mice after DS were adoptively transferred to T cell-deficient RAG1KO mice." (PMID 24223818, 2013).
infertile (1 paper, 2017). "Notably, all sperm samples from the infertile patients cohort recruited in this study express lowered level, but not complete absence of CCR6 and CatSper1." (PMID 29207656, 2017).
inflammatory skin disorder (1 paper, 2013). "The finding that CCR6-deficient mice fail to develop psoriasiform pathology following intradermal injection with IL-23 supports a critical role for CCR6 in this inflammatory skin disorder." (PMID 23472158, 2013).
IPEX syndrome (1 paper, 2021). "Interestingly, Treg express an affinity towards skin-homing through CCR4, CCR6, and cutaneous lymphocyte-associated antigen (CLA), a similar mechanism as seen in IPEX syndrome, caused by a Treg defect." (PMID 34080085, 2021).
ischemia (1 paper, 2021). A hypoperfusion of the BLOOD through an organ or tissue caused by a PATHOLOGIC CONSTRICTION or obstruction of its BLOOD VESSELS, or an absence of BLOOD CIRCULATION. "Surprisingly, Ccr6−/− mice demonstrated significantly reduced cardiac function and increased infarct sizes after ischemia/reperfusion." (PMID 34829761, 2021). "To investigate the role of CCR6 in AMI and cardiac injury, we performed coronary ischemia-reperfusion surgery in C57Bl/6 wild-type and Ccr6−/− mice." (PMID 34829761, 2021).
ischemic stroke (1 paper, 2022). A stroke disorder caused by obstruction of blood flow to the brain, due to thrombotic (local blood clot formation) or embolic (due to a blood clot or other material traveling from another site) event. "CCR6 activation is associated majorly with early IL-17 production in acute infections and after ischemic stroke, IL-17 triggers the expression of TNF-α and chemokines." (PMID 35453602, 2022). "CCR6 plays a role in neuroinflammation induced by ischemic stroke." (PMID 35453602, 2022).
Kaposi's sarcoma (1 paper, 2020). A malignant neoplasm characterized by a vascular proliferation which usually contains blunt endothelial cells. "For example, Kaposi’s sarcoma-associated herpesvirus (KSHV) induces CCR6 expression in human umbilical vein endothelial cells, which may contribute to the recruitment of dendritic cells (DCs) and lymphocytes into the Kaposi’s sarcoma lesion." (PMID 32986779, 2020).
kidney failure (1 paper, 2021). An acute or chronic condition that is characterized by the inability of the kidneys to adequately filter the blood. "Both antibody blocking of the CCL20–CCR6 pathway, as well as the use of CCR6-deficient mice in acute kidney injury experiments, were shown to increase the severity of kidney failure and mortality." (PMID 34356678, 2021).
latent infections (1 paper, 2013). "The alteration of CCR6 uses by viruses may influence the susceptibility of CD4+ CCR6+ T-cells and dendritic cell subsets in vivo and therefore, is important for viral pathogenesis in establishing latent infections, trafficking, and transmission." (PMID 24009735, 2013).
Lewis lung carcinoma (1 paper, 2022). "Additionally, transfection of Lewis lung carcinoma cells with CCR6 caused local production of CCL20 in the lung and reduced the metastatic possibility in mice." (PMID 36612054, 2022).
Löfgren’s syndrome (1 paper, 2023). "Interestingly, patients with Löfgren’s syndrome had increased levels of T-bet+ RORγt+ cells that produced IFN-γ and IL-17 A, co-expressed the chemokine receptors CXCR3 and CCR6, and their frequencies correlated with nonchronic disease." (PMID 37189479, 2023).
Lymphadenopathy (1 paper, 2017). Enlargement (swelling) of a lymph node. "CCR6 has been shown to be important for antigen-driven B-cell differentiation, which is seen in GC B-cells and memory B-cells, and the colocalization of TAGLN2 and CCR6 from the area of the GC to the perifollicular area was observed in SLE lymphadenopathy." (PMID 28910360, 2017).
male infertility (1 paper, 2017). The inability of the male to effect fertilization of an ovum after a specified period of unprotected intercourse. "The presently demonstrated critical role of the CCR6 and CatSper in mediating ligand-induced Ca2+ influxes required for various sperm functions suggests that CCR6 and CatSper could be markers for diagnosis of male infertility and a potential target for fertility control." (PMID 29207656, 2017).
mediastinal lymphoma (1 paper, 2007). "Recent findings suggest that expression of chemoattractants, such as CCL18, CCR6, and CCL20, on neoplastic epithelium in MNT can promote the recruitment of MALT, the emergence of monoclonal B cells, and, eventually, the subsequent development of mediastinal lymphoma." (PMID 17498299, 2007).
medullary breast carcinoma (1 paper, 2019). An infiltrating breast carcinoma with a relatively favorable prognosis. "The ligand for CCR6, CCL20 was higher in ductal and medullary breast carcinoma when compared to normal controls and other histological tissue types." (PMID 30850664, 2019).
meningitis (1 paper, 2014). A disorder characterized by acute inflammation of the meninges of the brain and/or spinal cord. "In summary, Ccr6−/− mice suffering from meningitis were affected more strongly than wild type mice, as evidenced by an increase in clinical score and increased mortality." (PMID 24699535, 2014).
mycobacteriosis (1 paper, 2016). "Indeed, CD4 T cell responses to Mtb are contained in a CXCR3+CCR6+ Th subset, cells that produce IFNγ, IL-2 and TNFα, and a mutation leading to the loss of the CXCR3+CCR6+ lineage specific transcription factor RORC leads to mycobacteriosis." (PMID 27409590, 2016). "A recent study underlined that bi-allelic RORC loss-of-function mutations resulted in the absence of IL-17-producing T cells and defective IFNγ production by circulating γδ T cells and CD4+CCR6+CXCR3+ αβ T cells, and was associated with mycobacteriosis." (PMID 27409590, 2016).
myeloma (1 paper, 2022). "It was reported that overexpression of CCl20 and CCR6 was also involved in the recruitment of Th17 in the bone microenvironment of myeloma patients." (PMID 36119497, 2022).
nasal polyps (1 paper, 2009). "This MIP-3α/CCL20/CCR6 positive-feedback loop involving Th17 cells, DCs, and fibroblasts amplifies the IL-17 inflammatory response in nasal polyps." (PMID 23283206, 2009).
nephritis (1 paper, 2021). Inflammation of renal tissue. "Although the roles of CCR6 and CXCR3 in the recruitment of Tregs into the kidney have already been established in similar antibody-mediated nephritis models, CCR4 in Tregs during the late phase has not been investigated." (PMID 32917984, 2021).
oral squamous cell carcinoma (1 paper, 2022). "In human oral squamous cell carcinoma, CCR6 expressing T-reg were more suppressive with higher FOXP3 expression compared to CCR6 negative T-regs." (PMID 36189219, 2022).
osteomyelitis (1 paper, 2025). An acute or chronic inflammation of the bone and its structures due to infection with pyogenic bacteria. "Overall, our study highlights the crucial immunomodulatory role that the CCL20/CCR6 axis plays during osteomyelitis." (PMID 40853122, 2025). "Implant-associated osteomyelitis in C57BL/6, CCL20-/-, and CCR6-/- mice revealed an early increase in planktonic bacterial growth on day 1 and increased bacterial loads in soft tissue and bone on day 14 post-infection in both CCL20-/- and CCR6-/- mice." (PMID 40853122, 2025). "However, the role of the CCL20/CCR6 axis in host defense against Staphylococcus aureus osteomyelitis remains unknown." (PMID 40853122, 2025).
Peptic ulcer (1 paper, 2021). The term peptic ulcer refers to acid peptic injury of the digestive tract, resulting in mucosal break reaching the submucosa. "The content of mature CCR6+ T-helper cells with pro-inflammatory activity significantly increases in the blood of patients with peptic ulcer associated with H. pylori infection." (PMID 34795977, 2021). "In this work, we studied CCR6+ T-helpers that were shown to increase in numbers in the blood of patients with peptic ulcer associated with H. pylori infection." (PMID 34795977, 2021). "We previously found that the number of CCR6+ T-helpers with the phenotype of effector/effector memory T cells increases in the blood of patients with H. pylori-associated peptic ulcer." (PMID 34795977, 2021). "The increase in the number of mature CCR6+ T-helper blood cells and their increased pro-inflammatory activity suggest the pathogenetic significance of these cells in H. pylori-associated peptic ulcer disease." (PMID 34795977, 2021). "The aim of the study was to evaluate changes in the blood level of pro-inflammatory types of mature CCR6+ T-helpers in H. pylori-associated peptic ulcer disease." (PMID 34795977, 2021). "Activation of purified CCR6+ T-helper cells ex vivo revealed an increased content of Th1, Th17, and Th1/Th17 in patients with peptic ulcer disease." (PMID 34795977, 2021).
peritonitis (1 paper, 2023). Inflammation of the peritoneum (tissue that lines the abdominal wall and covers most of the organs in the abdomen). "CCR6 deficiency in a murine model altered the innate response via attenuating inflammatory response during peritonitis with lower NO production in macrophages after LPS stimulation." (PMID 36825028, 2023).
polyp (1 paper, 2016). A usually exophytic mass attached to the underlying tissue by a broad base or a thin stalk. "Consistent with the high frequency of IL-17+ cells, an abundance of CCR6-expressing cells was also found in both healthy nasal mucosa and polyp explants." (PMID 26684290, 2016).
primary progressive multiple sclerosis (1 paper, 2024). A multiple sclerosis that is characterized by steady worsening of neurologic functioning, without any distinct relapses or periods of remission. "However, CCR5+, CXCR3+, CCR6+ and CCR4+ cells within the CD4+ CD45RA− memory T-cell pool of the CSF of OCR-treated people with primary progressive multiple sclerosis were all depleted for CD20dim T cells, which was not the case for the CD8+ memory T-cell pool." (PMID 38385000, 2024).
pulmonary fungal infection (1 paper, 2012). "Thus, CCR6 mediates the recruitment of Tc17 cells to the lung during recall after pulmonary fungal infection." (PMID 22829762, 2012).
radiodermatitis (1 paper, 2022). A cutaneous inflammatory reaction occurring as a result of exposure to biologically effective levels of ionizing radiation. "Irradiated CCR6−/− mice also displayed dramatically reduced radiodermatitis, with significant reductions in keratinocyte hyperplasia, acanthosis, and neutrophil (Ly6b+) infiltration in comparison to irradiated WT controls." (PMID 35785521, 2022). "Nevertheless, despite reductions in cytokine signaling and radiodermatitis in CCR6−/− mice, Ccl20 mRNA upregulation remained elevated in comparison to naive WT controls, indicating the persistence of pro‐inflammatory signals in these mice." (PMID 35785521, 2022). "However, as previously reported, γδT cells, which constitutively express CCR6 that is necessary for their recruitment to the inflamed skin, are also reportedly important effectors of radiodermatitis in mice." (PMID 35785521, 2022).
retinal (1 paper, 2025). "When CCR-6, the receptor of MIP-3-alpha, was knocked out, retinal pathologies and inflammation were significantly reduced, concluding that inflammation is associated with MIP-3-alpha expression following trauma." (PMID 40074940, 2025).
Rotavirus infection (1 paper, 2015). Infection with any of the rotaviruses. "The importance of the CCR6-CCL20 axis was also verified in CCR6 double negative mice showing decreased intestinal M-cell numbers and low IgA secretion upon rotavirus infection." (PMID 25944986, 2015).
SARS-CoV infection (1 paper, 2014). "The receptor for CCL20, CCR6 was significantly down regulated with age and SARS-CoV infection on peripheral blood DCs (2-way ANOVA for age and d.p.i.)." (PMID 24642138, 2014).
severe combined immunodeficiency (1 paper, 2013). Severe combined immunodeficiency (SCID) comprises a group of rare monogenic primary immunodeficiency disorders characterized by a lack of functional peripheral T lymphocytes resulting in early-onset severe respiratory infections and failure to thrive. "In a Rag1−/− severe combined immunodeficiency (SCID) model where CCR6−/− or WT TH17 cells were transferred in, a reduction in both TH17 and Treg cells were seen in the recipient mice receiving the CCR6−/− cells." (PMID 23874340, 2013).
Sjögren's syndrome (1 paper, 2023). "As CXCR5+CCR6+ TFH cells may participate in the antibody‐associated immune responses in Sjögren's syndrome, our results indicate the involvement of this TFH subset in SL‐induced immune dysregulation." (PMID 37132178, 2023).
skin cancer (1 paper, 2022). "Immunohistochemical analysis of chemokine receptor expression patterns in non-melanoma skin cancer demonstrated downregulation of CCR6 and upregulation of CCR7 and CXCR4 in potentially metastatic non-melanoma skin cancer." (PMID 35203305, 2022).
skin infection (1 paper, 2014). An inflammatory process affecting the skin, caused by bacteria, viruses, parasites, or fungi. "A significant functional role of CCR6 has only been shown for macrophage attraction and subsequent T-cell activation in response to skin infection of mice with Salmonella species." (PMID 24699535, 2014).
TAFRO syndrome (1 paper, 2025). "Additionally, glycogen synthase kinase 3β (GSK3β) and CC chemokine receptor 6 (CCR6) have been identified as upstream positive regulators of TAFRO syndrome, which could serve as both diagnostic markers and therapeutic targets for TAFRO syndrome." (PMID 40248702, 2025).
ulcer (1 paper, 2021). "In this work we determine the number of mature Th1, Th17, and Th1/Th17 in CCR6+ T-helpers separated from the blood of healthy donors and ulcer patients." (PMID 34795977, 2021). "Activation of CCR6+ T-helpers purified from blood of ulcer patients revealed an increased content of Th1, Th17, and Th1/Th17." (PMID 34795977, 2021).
viral myocarditis (1 paper, 2017). Myocarditis that is caused by an infection with a viral agent. "Furthermore, the administration of a CCL20-neutralising antibody improved the prognosis in CVB3-induced acute viral myocarditis by decreasing CCR6+ Th17 cell recruitment." (PMID 28798316, 2017).
ZIKV infection (1 paper, 2022). "On the other hand, in women with a history of ZIKV infection, CCR6+ DN cells were the favored subpopulation." (PMID 35215843, 2022).